ZEB1 (zinc finger E-box binding homeobox 1)
Diseases named in the same sentence as ZEB1 in open-access papers (continued):
Sharing a sentence is not in itself a finding about the gene and the disease.
tumor (continued). "Furthermore, the treatments with si-ZEB1 plus L-OHP resulted in reduced tumor growth rate, indicating that ZEB1 knockdown could effectively attenuate the development of EC." (PMID 33292221, 2020). "However, it is largely unknown how signals from the tumor microenvironment (TME) contribute to aberrant Zeb1 expression." (PMID 33046710, 2020). "The results showed that upregulation of circIFI30 could enhance the expressions of CD44, Twist and ZEB1 as well as decrease the expression of E-cad in xenograft tumor tissues, whereas knockdown of circIFI30 played an opposite role compared with the control group." (PMID 32497020, 2020). "Moreover, α-SMA (a pericyte marker) staining and dextran leakage assay demonstrated remarkedly increased perivascular coverage and reduced dextran leakiness in PyMT;Zeb1cKO tumors, revealing a critical role for Zeb1 in the maintenance of tumor vessel normalization and vascular integrity." (PMID 33046710, 2020). "Besides, inhibition of ZNRD1‐AS1 attenuated tumor growth via modulating miR‐194 and ZEB1 in vivo." (PMID 32862492, 2020). "This is consistent with models proposed in carcinoma, where ZEB1 may promote stemness features (partial EMT state associated with tumor initiation) but not necessarily invasive/EMT features, these two features being uncoupled." (PMID 32759677, 2020). "To precisely assess the impact of stromal fibroblast-derived ZEB1 on the growth and invasion of mammary epithelial tumours in vivo, we orthotopically injected 2 × 106 PyMT-cancer cells into the fat pads of Fib-WT and Fib-cKO mice with tumour growth and invasion monitored." (PMID 31324807, 2019). "However, the role of stromal ZEB1 in tumour progression remains unexplored." (PMID 31324807, 2019). "Moreover, miR-23b-3p acted as a tumor inhibitor by targeting Zeb1 in bladder cancer." (PMID 31097683, 2019). "The hallmark of EMT is the repression of E-cadherin by Zinc finger E-box-binding homeobox 1 (ZEB1) and Snail TF-family members and induction of matrix metalloproteases (MMP) resulting in enhanced motility/plasticity, invasiveness as well as increased resistance to apoptosis of tumor cells." (PMID 30863498, 2019). "Moreover, we also investigate the contribution of this PKCα/ZEB1 axis into the establishment and maintenance of the mesenchymal state and how PKCα-dependent modulation of ZEB1 levels controls tumor aggressiveness and metastasis using in vitro and in vivo models." (PMID 31828042, 2019). "Furthermore, down-regulation of ZEB1 decreased OS cell invasion and proliferation, illustrating that the tumor suppressive role of miR-409-3p in OS cells may be exerted via negative regulation of ZEB1." (PMID 30846940, 2019). "Indeed, tumor buds have been shown to have reduced E‐Cadherin expression, to lose membrane β‐catenin expression and to overexpress EMT associated biomarkers like zinc finger E‐box-binding homeobox 1 and 2 (ZEB1 and ZEB2), SNAIL and N-Cadherin." (PMID 31295960, 2019). "An important conclusion of this study is that only subtle changes in Zeb1 expression, to the degree conferred by dosage-dependent miR-200c regulation, are sufficient to induce a strong effect on EMT and cancer progression in two tumor-susceptible genetic backgrounds, the RT2 and KPC models." (PMID 30405106, 2018). "The signals from primary tumor associated stroma such as TGF-β1 may trigger changes in cytoskeleton reorganization and lead to the activation of nuclear transcription factors, ZEB1, TWIST1 and TWIST2, which, once activated, implement EMT program and promote invasiveness." (PMID 29337896, 2018).
tumor (continued). "Importantly, these molecular signatures of EMT were already detected in islets of 6-week-old mice, before tumor development, suggesting that they were all driven by miR-200 loss and Zeb1 overexpression and not by secondary mutations." (PMID 30405106, 2018). "In addition, ZEB1 transfection was performed in primary cell cultures from PCa tumor explants." (PMID 30065348, 2018). "Concerning miR-200 family, it has been reported that miR-200c inhibits protein Zinc finger E-box-binding homeobox 1 (ZEB-1) and miR-200a inhibits ZEB-2, proteins that are important transcription factors that allow epithelial–mesenquimal transition and associated with tumor progression." (PMID 28245631, 2017). "Having a dual role in potentiating EMT and anoikis resistance as described here, the ZEB1/TLE1-mediated transcriptional silencing of the tumor suppressive E-cadherin expression represents an important molecular event that may impact the initiation and progression of lung malignancy." (PMID 29069783, 2017). "Since tumor-associated microglia and macrophages are the most abundant population of immune cells found in GBM, we further investigated mutual exclusivity of ZEB1 with CD68 or HLA-DR (as a marker of activated microglia and macrophages) in additional GBM cases (N = 8) using co-labeling." (PMID 28945795, 2017). "Therefore ZEB1 may play a similar role in OS tissues and its expression and functions may be inhibited by tumor suppressor miR-429." (PMID 28694763, 2017). "In addition, the expression of Zeb1 is increased along with Snail in tumor cells undergoing EMT." (PMID 29250491, 2017). "Furthermore, miR-429 can directly down-regulate the EMT inducer ZEB1 expression, so tumor suppressor miR-429 may repress the progression and metastasis of OS at least partially through inhibiting ZEB1 expression." (PMID 28694763, 2017). "We did not observe associations between ZEB1 and other clinical parameters such as tumor stage, nodal stage, HER2 status, hormone receptor status, histological type, localization of metastasis, or therapies (chemo‐, hormone‐, radio‐, or herceptin therapy) (all P > 0.1)." (PMID 28700115, 2017). "In order to analyze whether epithelial to mesenchymal transition (EMT) affects metabolic pathways in GBMs, we established stable tumor models with suppressed expression of the core EMT activator ZEB1 in three GBM cell lines (LN229, GBM1 and JHH520) through RNA interference technology." (PMID 27705917, 2016). "Zeb1, an important transcriptional suppressor of EMT, was found to be positively correlated with migration ability in SKOV-3 and HO8910 EOC cell lines, and the down-regulation of Zeb1 with shRNA) in SKOV-3 cells could significantly decrease tumor growth in mice xenograft." (PMID 27304054, 2016). "In contrast, in a recent report depicting six master regulators (AEBP1, HOPX, PRRX1, SNAI2, ZEB1, ZEB2) of the TCGA “mesenchymal” subtype, they employed a network-based strategy to uncover the molecular mechanism underlying the discrete mesenchymal subtype in whole tumor tissues of serous OC." (PMID 27081703, 2016). "Aggressive tumor cells are often resistant to chemotherapeutic agents and may undergo the epithelial-mesenchymal transition (EMT) process through increases of zinc finger E-box binding homeobox 1/2 (Zeb1/2), snail, and twist, and the loss of E-cadherin." (PMID 25714015, 2015). "Therefore, ZEB1 might provide single tumor cells in the primary tumor with the ability to metastasize to the bone, where these cells are selected and enriched due to their bone metastasis favoring gene expression profile." (PMID 25973542, 2015). "Furthermore, in a cohort of 88 ESCC tumor samples with which the expression status of miR-200b had been examined in our previous study, we found a significant inverse correlation between the expression levels of ZEB1/2 and that of miR-200b (P < 0.05)." (PMID 26334393, 2015).
tumor (continued). "In this study, we revealed that the miR-200b-ZEB1/2 axis contributes to the pathobiology of ESCC via an EMT-independent mechanism, whereas suppression of the Kindlin-2-integrin β1-AKT regulatory axis is an alternative mechanism underlying the tumor suppressor function of miR-200b in ESCC." (PMID 26334393, 2015). "Also, our tumor samples included both malignant and non malignant cells that may differ in miR-200c expression and ZEB1 protein expression." (PMID 25329395, 2014). "In addition, both xenografts and patients tumor tissues displayed pSMAD2 and ZEB1 staining." (PMID 25275602, 2014). "The results from the tumor area and tumor metastasis counts in lungs suggested that the synergism antitumor efficacy was found in mice immunized with the tumor vaccine B16F10/GPI-IL-21 in combination with either overexpression of miR200c or knockdown of ZEB1 in B16F10 cells." (PMID 24625224, 2014). "Notably, the PMN infiltrate correlated with expression of the tumor cells of ZEB1." (PMID 23227088, 2012). "Following treatment with PMN or PMN-derived elastase, the tumor cells not only lost contact with each other, they also underwent EMT, as determined by established markers for EMT, including loss of keratins, translocation into the nucleus of β-catenin, and upregulation of ZEB1." (PMID 23227088, 2012). "For example, the ∼1.5-fold increase in Zeb1 mRNA in pancreatic islets, accompanied by a ∼1.3-fold increase in ZEB1 protein, is sufficient to promote EMT, tumor invasion, and increased metastasis in two different autochthonous cancer models." (PMID 41533591, 2026). "In line with this, transcription factor activity analysis revealed significantly higher activities of EMT-related transcription factors, such as ZEB1 and TWIST118, in C8 tumor cells." (PMID 39794332, 2025). "In vitro, ZEB1 has been shown to promote the proliferation, colony formation, sphere formation and migration of CCA cells and markedly enhance tumor progression in vivo." (PMID 41303618, 2025). "Zinc-finger E-box-binding homeobox 1 (ZEB1) has been identified as a crucial inducer of epithelial-to-mesenchymal transition (EMT), which contributes to promoting tumor proliferation and metastasis." (PMID 40990019, 2025). "In primary tumors, both ZEB1 and ITIH2 were highly expressed at the invasive front of the tumor edge compared with the central region, indicating that they promote invasive potential." (PMID 40178908, 2025). "WB assays also confirmed that treatment with rhSFRP1, rmSFRP1, and CM from CAF-Sfrp1 enhanced tumor stemness and EMT activity, as evidenced by upregulation of CD44, CD133, ZEB1, Vimentin, and N-cadherin, along with the downregulation of E-cadherin." (PMID 40225580, 2025). "ZEB1 promoted the expansion of Th17 cells via upregulating factors (IL-23 and TGF-β), which secretes IL-17 cytokines in AML cells, thereby promoting tumor growth and immune suppression, thus contributing to AML progression." (PMID 39941895, 2025). "The transcription factor ZEB1 and the STAT3 signaling pathway play crucial roles in EMT, tumor invasion, immune regulation, and chronic inflammatory responses." (PMID 40016707, 2025). "It has been noted that miR-200b is partially silenced through DNA methylation, which allows it to inhibit tumor growth and invasion by directly targeting BMI1 and ZEB1 in HCC." (PMID 39829957, 2025). "In the colon-derived cells, during the transition from a healthy to a tumor cell and then to a metastatic cell type, we observed a gradual increase in the EMT-TF genes SNAI2 and ZEB1, and in VIM, CDH5 and MMP2." (PMID 40332096, 2025). "In the tumor microenvironment, STAT3 and ZEB1 form a feedback loop that promotes EMT and enhances the invasive characteristics of tumor cells." (PMID 40016707, 2025). "Immunohistochemical analyses revealed distinct tumor microenvironment features in DPP-4i users, including increased Zeb1+ tumor cells, reduced CD3+ and CD8+ T cell infiltration, and fewer tertiary lymphoid structures (p < 0.001)." (PMID 40282969, 2025).
tumor (continued). "Zinc Finger E-box Binding Homeobox 1 (ZEB1) is a transcription factor that plays a pivotal role in epithelial-mesenchymal transition (EMT), tumor progression, and vascular remodeling." (PMID 41348701, 2025). "STAT3 is an important transcription factor in tumor progression, and its activation is pivotal in regulating the expression of EMT-related genes/proteins, such as Twist, Vimentin, Snail, MMPs, and ZEB1, essential proteins in metastasis." (PMID 39412616, 2025). "Our scRNA-Seq atlas analysis of TIME in vivo revealed that inhibition of ZEB1 not only increased the CD8+ T cell population but also decreased the proportion of granulocytes (neutrophils) and their interaction with tumor cells." (PMID 40924501, 2025). "In conclusion, our studies confirmed that DNMT3a acted as a tumour promoter to induce malignant progression of LUAD by upregulating HDAC7 and further inducing the upregulation of ZEB1 and c-Myc." (PMID 39990668, 2025). "In this specific tumor subset MMP9, together with MMP2 and ZEB1, were more related to the metastatic subtype of this tissue." (PMID 40332096, 2025). "Consistently, ZEB1-dependent CCL2 abundance correlated with CTL influx and tumor cell killing in metastatic lung colonies." (PMID 40595293, 2025). "This study aims to investigate the expression of E-cadherin and ZEB1 as critical markers in PTC, particularly their roles in lymph node metastasis, tumor progression, and EMT." (PMID 40787244, 2025). "In parallel, mRNA expression levels of ZEB1, a key transcription factor involved in WNT signaling, stem cell maintenance and tumor–stroma interactions were quantified for each sample." (PMID 40856386, 2025). "Several studies demonstrated that MSCs contribute also to tumor invasiveness and progression by regulating EMT regulators, like Twist, Snail and Zinc finger E-box binding homeobox 1 (ZEB1)." (PMID 39981232, 2025). "RAC2 contributes to EMT and metastasis by mediating cytoskeletal reorganization and activating pro-tumor pathways like PI3K/AKT and JNK/ZEB1." (PMID 40072059, 2025). "Extensive research has elucidated the role of ZEB1 in HCC, demonstrating that it acts as a tumor promoter by facilitating metastasis, the Warburg effect, chemoresistance, and impeding tumor cell apoptosis." (PMID 40771411, 2025). "Conversely, EMT-transformed tumor cells reinforce TAM recruitment and M2 polarization through immunomodulatory factors such as CCL2 and ZEB1, thereby establishing a bidirectional interplay that fuels tumor progression." (PMID 40304000, 2025). "Using qRT-PCR, we observed a decrease in E-cadherin and an increase in mesenchymal markers such as Slug, N-cadherin, vimentin, ZEB1, and ZEB2 in LNCaP cells treated with periprostatic tumor fat medium, indicating epithelial–mesenchymal transition." (PMID 40437336, 2025). "We validated that Ntn1 cKO reduced the expression of Zeb1, Vim, and Sox9 in KPC tumor cells, using qRT-PCR of FACS-sorted tdtomato-labeled tumor cells from Rosa26-LSL-tdtomato; KPC or KPCN mice." (PMID 40777309, 2025). "Zinc finger E-box-binding homeobox 1 and E-cadherin are key biomarkers in PTC, strongly correlating with lymph node metastasis, tumor grade, and clinical stage." (PMID 40787244, 2025). "In summary, our data show that ZEB1 in macrophages promotes CD8+ cell infiltration into s.c. tumors and metastatic colonies in the lung, preceding tumor cell death to counteract tumor outgrowth." (PMID 40595293, 2025). "IHC analysis corroborated these findings, with reduced staining intensity for mesenchymal markers (Vimentin, N-cadherin, ZEB-1) and increased intensity for E-cadherin observed in ARPC1B-knockdown tumor tissues (Fig. A7C)." (PMID 41050079, 2025). "The identification of gene co-expression modules containing classical EMT markers (e.g., VIM, ZEB1, SNAI2) alongside ECM-related genes (COL1A1, FN1, SPARC, LOX) underscores a tightly coordinated interaction driving tumor cell plasticity and invasion." (PMID 40943497, 2025).
tumor (continued). "By targeting ZEB1 and ZEB2, miR-200c promotes the maintenance of epithelial characteristics in cells, thereby acting as a tumor suppressor." (PMID 39859424, 2025). "Hypoxia also elevates ZEB1/2 activity, increasing the proportion of CD44+CD117+ cancer stem cells from 5% to 18%, thereby enhancing tumor invasiveness." (PMID 40474872, 2025). "First, CAFs directly promote tumour proliferation and metastasis by secreting growth factors (e.g., CXCL11, CCL5): CAF-derived CCL5 enhances HCC metastasis by triggering the HIF1α/ZEB1 axis, while CXCL11 directly promotes HCC cell proliferation." (PMID 40495147, 2025). "Mechanistically, we found that SB218078 suppresses tumor angiogenesis by blocking the activation of VEGFR2 and ZEB1." (PMID 40160462, 2025). "IHC results obtained from xenograft tumor sections showed decreased levels of DEC1, ZEB1, N-cadherin, Vimentin, Snail1 and Ki67 in DEC1 KD tumor tissue compared to control sections." (PMID 40133270, 2025). "Subsequently, the gain of expression of mesenchymal marker vimentin in tumor cells revealed the induction of EMT in the sgP19/kRAS model, and it is induced by activating the TGFβ/ZEB1 signaling pathway." (PMID 41354626, 2025). "Specifically, USP39 promotes HCC progression by inhibiting the degradation of ZEB1 through its deubiquitylation function, whereas TRIM26 exerts tumor suppressor functions by ubiquitinating degraded ZEB1." (PMID 40990019, 2025). "As a transcription factor, ZEB1 plays a crucial role in driving epithelial‐mesenchymal transition (EMT), facilitating tumor invasion and metastasis." (PMID 40556338, 2025). "The EMT process is a prerequisite for tumor invasion and is regulated by several transcription factors, including SNAIL1/2, ZEB1/2, and TWIST." (PMID 40955778, 2025). "ZEB1 is predominantly recognized for its role in driving the epithelial-to-mesenchymal transition (EMT) in cancer cells, a process that promotes tumor progression." (PMID 39193340, 2024). "miR-144 was significantly down-regulated in NSCLCs from HPR; miR-144 targets oncogene Zeb1; overexpression of miR-144 inhibits NSCLC cell migration and tumor progression." (PMID 39440184, 2024). "For instance, Fat1 deletion stabilizes hybrid EMT in SCC, increasing tumor aggressiveness by activating YAP1 and ZEB1 while preserving epithelial fate." (PMID 38324529, 2024). "Here, we found that hypoxia-induced ZEB1 expression is closely correlated with CD47-SIRPα axis activity in CSCC, which enables cancer cells to evade phagocytosis by macrophages and promotes tumour progression." (PMID 38183060, 2024). "The western blotting results suggested that SRSF9 silencing decreased ZEB1, USP22, and N-cadherin expression levels but increased E-cadherin expression levels in tumor tissues." (PMID 39530604, 2024). "Tumor tissue lysates from LV-shRNA and LV-shRNA-BRCC3 mice were subjected to IP with anti-ZEB1 antibody, followed by western blot analysis with anti-ubiquitin antibody." (PMID 38449391, 2024). "ZEB1 is a core EMT-transcription factor and is frequently upregulated at the invasive front of CRC and other cancer entities, where it orchestrates tumor stemness, metastasis, and therapy resistance." (PMID 38937629, 2024). "The crosstalk of TGFβ with Wnt, NFkB, Notch or hypoxia signaling pathways orchestrates tumor-specific EMT progression through SMADS, SNAI1/2, TWIST, and ZEB1/2 factors." (PMID 39075581, 2024). "The proliferative activity (Ki67) of tumor cells was lower in the KPC/TFF1KO mice, whereas the labelling index of the EMT markers Snail and ZEB1 was significantly higher in the KPC/TFF1KO mice than the other mice." (PMID 38872370, 2024).